TDRD1 (tudor domain containing 1)
Description:
Plays a central role during spermatogenesis by participating in the repression transposable elements and preventing their mobilization, which is essential for the germline integrity. Acts via the piRNA metabolic process, which mediates the repression of transposable elements during meiosis by forming complexes composed of piRNAs and Piwi proteins and governs the methylation and subsequent repression of transposons. Required for the localization of Piwi proteins to the meiotic nuage. Involved in the piRNA metabolic process by ensuring the entry of correct transcripts into the normal piRNA pool and limiting the entry of cellular transcripts into the piRNA pathway. May act by allowing the recruitment of piRNA biogenesis or loading factors that ensure the correct entry of transcripts and piRNAs into Piwi proteins (By similarity).
Synonyms: CT41.1
Tractability: Small molecule: a structure with a bound ligand is known.
Gene: Protein-coding gene on chromosome 10 (114,179,270 to 114,232,666, forward strand). Ensembl gene ENSG00000095627.
Subcellular location: Cytoplasm
Pathways (Reactome):
Gene expression (Transcription): PIWI-interacting RNA (piRNA) biogenesis
Gene Ontology:
Biological process: germ cell development; P granule organization; piRNA processing; spermatogenesis; transposable element silencing by piRNA-mediated DNA methylation
Cellular component: cytoplasm; P granule; pi-body; chromatoid body; ribonucleoprotein complex; synapse
Genetic constraint (gnomAD): Loss-of-function variants: 31 observed, 108.18 expected, observed/expected ratio (o/e) 0.29, 90% interval 0.21 to 0.39. The upper end of that interval is the gene's LOEUF score, 0.39, which puts it in group 1 of 6, group 1 being the genes least tolerant of losing a copy. Missense variants: 1,018 observed, 1,206.2 expected, observed/expected ratio (o/e) 0.84, 90% interval 0.8 to 0.89. Synonymous variants: 423 observed, 415.61 expected, observed/expected ratio (o/e) 1.02, 90% interval 0.94 to 1.1.
Homologues: Orthologues: chimpanzee TDRD1 (99% identical), macaque TDRD1 (96% identical), pig TDRD1 (80% identical), dog TDRD1 (80% identical), rabbit TDRD1 (78% identical), guinea pig TDRD1 (73% identical), rat Tdrd1 (72% identical), mouse Tdrd1 (72% identical), tropical clawed frog tdrd1 (35% identical), zebrafish tdrd1 (30% identical). Paralogues in human: TDRD6 (20% identical), TDRD15 (19% identical), TDRD7 (13% identical), TDRD5 (10% identical), TDRKH (7% identical), TDRD10 (4% identical).
Diseases named in the same sentence as TDRD1 in open-access papers:
TDRD1 is named in the same sentence as 24 diseases in open-access papers, as found by Europe PMC text mining. Sharing a sentence is not in itself a finding about the gene and the disease. The quoted sentences say what the papers report.
prostate carcinoma (13 papers, 2013 to 2023). A carcinoma that arises from epithelial cells of the prostate gland. "Tdrd1 is a direct gene target of the transcription factor Erg that is strongly associated with primary prostate cancer." (PMID 30596102, 2018). "In conclusion, we report here that overexpression of ERG transcription factor in TMPRSS2:ERG-positive prostate cancer induces a loss of DNA methylation at the TDRD1 promoter-associated CpG island." (PMID 23555854, 2013). "TDRD1 is closely associated with ERG overexpression in primary prostate cancer." (PMID 32828126, 2020). "Given the prevalence of ERG fusions, TDRD1 overexpression is a common alteration in human prostate cancer which may be exploited for diagnostic or therapeutic procedures." (PMID 23555854, 2013). "High TDRD1 expression was strongly correlated with better PFS but it is currently unknown what its functional role is in cancer other than strong association with ERG expression in prostate cancer." (PMID 33374923, 2020). "Taken together, this study represents the first characterization of TDRD1 functions in prostate cancer development and suggests TDRD1 as a potential therapeutic target for prostate cancer treatment." (PMID 36865141, 2023). "TDRD1, a germ cell-specific gene, is erroneously expressed in more than half of prostate tumors, but its role in prostate cancer development remains elusive." (PMID 36865141, 2023). "Ablation of TDRD1 in prostate cancer cells disrupted the integrity of Cajal bodies, affected the snRNP biogenesis, and reduced cell proliferation." (PMID 36865141, 2023). "This supports the recent finding that the combination of three genes (HOXC6, DLX1, and TDRD1) constitutes the top prognostic marker for prostate cancer." (PMID 27833659, 2016). "The promoter of TDRD1 is hypomethylated and TDRD1 becomes overexpressed in ERG overexpressing prostate cancer cells." (PMID 24739220, 2014). "A similar relationship was observed with ERG expression and methylation status of its target gene namely TDRD1 in prostate cancer." (PMID 24664224, 2014). "Based on these initial results, we decided to use VCaP cells as an in vitro model to study the mechanistic relation between ERG and TDRD1 genes in ERG-rearranged prostate cancer." (PMID 23555854, 2013). "Here, we report that ERG and TDRD1 are co-expressed in human prostate cancers and we provide a mechanistic explanation for the observed co-expression." (PMID 23555854, 2013). "Accordingly, demethylation of the TDRD1 promoter in TMPRSS2:ERG-negative prostate cancer cells by DNA methyltransferase inhibitors resulted in TDRD1 induction." (PMID 23555854, 2013). "Despite hardly detectable PIWIL1-4 expression, we decided to test the extent of TDRD1 influence on LINE1 retrotransposition activity in prostate cancer cells." (PMID 23555854, 2013). "Our previous expression profiling study of human prostate cancer specimens revealed that TDRD1 is, apart from ERG, the most differentially expressed gene between TMPRSS2:ERG-negative and -positive tumors." (PMID 23555854, 2013). "One of the important questions brought up by this study concerns the consequences of TDRD1 accumulation in ERG-rearranged prostate cancer." (PMID 23555854, 2013). "At present, there are no studies of TDRD1 in OC however, TDRD1 is now considered a potential biomarker for prostate cancer as it strongly associates with expression of the frequently mutated transcription factor, ERG." (PMID 33374923, 2020). "As a result, TDRD1 becomes transcriptionally activated in TMPRSS2:ERG-positive prostate cancer." (PMID 23555854, 2013). "Herein, we describe the co-expression of ERG and TDRD1 in prostate cancer in vitro and in vivo." (PMID 23555854, 2013). "Among genes deregulated in ERG-rearranged prostate cancer, at least two independent studies identified Tudor domain-containing protein 1 (TDRD1) as the most differentially expressed gene between ERG rearrangement-positive and -negative prostate cancer, apart from ERG itself." (PMID 23555854, 2013).
prostate carcinoma (continued). "To test if TDRD1 may interact with PIWI proteins in TMPRSS2:ERG-positive prostate cancer and thus contribute to the piRNA pathway activity, we measured the mRNA expression of human PIWIL genes in prostate cancer cell lines." (PMID 23555854, 2013). "Thus, the possibility of other factors controlling TDRD1 expression in prostate cancer cells cannot be excluded." (PMID 23555854, 2013). "This suggests that the co-expression of ERG and TDRD1 is specific for prostate cancer." (PMID 23555854, 2013). "Finally, our data suggest that TDRD1 overexpression in ERG-rearranged prostate cancer has a potential of being exploited as a target for prostate cancer immunotherapy." (PMID 23555854, 2013). "Of note, the average level of TDRD1 promoter methylation was inversely correlated with TDRD1 mRNA levels across all 93 samples (ρ = -0.57), suggesting that loss of promoter methylation substantially contributes to TDRD1 overexpression in TMPRSS2:ERG fusion-positive prostate cancer." (PMID 23555854, 2013). "Tudor domain-containing protein 1 gene (TDRD1) was reported to be differentially expressed between TMPRSS2:ERG-negative and TMPRSS2:ERG-positive prostate cancer." (PMID 23555854, 2013). "TDRD1 has been discovered to be a direct target of (ETS-related gene) ERG, which promotes tumor initiation and progression in TMPRSS2-ERG fusion prostate cancer and could be a new immunotherapy target." (PMID 36439479, 2022). "Some of these genes were already extensively studied in prostate cancer, mostly those upregulated in tumor tissue: SPINK1 (Top17, logFC 4.8), ETV4 (Top63, logFC 3.6), PCA3 (Top79, logFC 3.5), TDRD1 (Top86, logFC 3.4), AMACR (Top105, logFC 3.2), DLX1 (Top110, logFC 3.1), HOXC6 (Top268, logFC 2.3)." (PMID 31170942, 2019). "Irrespective of the possible functional involvement of TDRD1 in prostate cancer, TDRD1 overexpression has a potential of being exploited in prostate cancer therapy." (PMID 23555854, 2013). "In contrast, TDRD1 was not co-expressed with ETV1 (r2 = 0.05) which is an ETS transcription factor found to be sporadically rearranged in prostate cancer." (PMID 23555854, 2013). "This view is further supported by a repression of TDRD1 expression accompanied by complete CpG methylation in benign prostate tissues and fusion-negative prostate cancer." (PMID 23555854, 2013). "Our findings suggest that TDRD1 does not contribute to the control of LINE1 activity in prostate cancer cells, as it is unlikely that the piRNA pathway is functional these cells." (PMID 23555854, 2013). "We thus propose that overexpression of TDRD1, observed by us and others in 100% of TMPRSS2:ERG-positive prostate tumors, makes TDRD1 a promising target for immunotherapy of ERG rearrangement-positive prostate cancer." (PMID 23555854, 2013). "For example, Tudor domain-containing protein 1 (TDRD1) was found to differentially regulate between fusion-positive and fusion-negative prostate cancer cells." (PMID 24739220, 2014). "In contrast to prostate cancer, there was no co-expression of ERG and TDRD1 in any of these studies (r2 = 0.03 and 0.02, respectively)." (PMID 23555854, 2013). "In contrast to our observations in prostate cancer (r2 = 0.84), ERG and TDRD1 were not co-expressed in CA-AML (r2 = 0.07)." (PMID 23555854, 2013). "Gene expression measurements by real-time quantitative PCR revealed a remarkable co-expression of TDRD1 and ERG (r2 = 0.77) but not ETV1 (r2<0.01) in human prostate cancer in vivo." (PMID 23555854, 2013). "Accordingly, overexpression of TDRD1 in ERG-negative LNCaP cells did not lead to changes in cell viability (data not shown), suggesting that expression of TDRD1 is not required for proliferation of ERG-rearranged prostate cancer cells in vitro." (PMID 23555854, 2013).
prostate tumors (4 papers, 2013 to 2023). "We inspected methylation of DNA around the TDRD1 transcription start site in prostate tumors, that we had analyzed by MeDIP-Seq, and found this region to be differentially methylated between tumors with and without the TMPRSS2:ERG gene fusion." (PMID 23555854, 2013). "The aim of our study was to provide a mechanistic explanation for the transcriptional activation of TDRD1 in ERG rearrangement-positive prostate tumors." (PMID 23555854, 2013). "TDRD1 is over-expressed in majority of 131 primary prostate tumors patients." (PMID 31576243, 2019). "In addition, Shaikhibrahim and colleagues reported the overexpression of TDRD1 as an epigenetics-related gene in poorly and moderately differentiated prostate tumors, compared to normal glands." (PMID 27196083, 2016). "In conclusion, a constant presence of ERG is required to maintain high expression of TDRD1 in VCaP cells and the observed co-expression of the two genes in prostate tumors could be explained by a unidirectional activation of TDRD1 through the ERG transcription factor." (PMID 23555854, 2013). "Comparison of TDRD1 mRNA levels to the DNA methylation of the CpG-island at the TDRD1 promoter revealed an inverse correlation between the two parameters across the investigated cell lines, which was in accordance with the corresponding data from prostate tumors." (PMID 23555854, 2013). "Previous studies have identified TDRD1 as the most differentially expressed gene between ERG-negative and ERG-positive prostate tumors besides ERG." (PMID 23555854, 2013). "Close inspection of data reveals that in several prostate tumors tested negative for the TMPRSS2:ERG rearrangement, TDRD1 is expressed at high levels despite low ERG expression, suggesting that ERG may not be the only factor which is capable of activating TDRD1 transcription." (PMID 23555854, 2013).
infertile (3 papers, 2012 to 2016). "In this context, it is interesting to note that a recently published study reported TDRD1 promoter to be hypermethylated in infertile male patients with spermatogenic disorders, linking TDRD1 promoter methylation and TDRD1 expression to human disease." (PMID 23555854, 2013). "In addition, gain of methylation in spermatogenesis-related gene promoters, including DAZL, PIWIl2 and TDRD1, is observed in spermatozoa and testicular samples from infertile human patients." (PMID 27880848, 2016). "The repression of PIWIL2 and TDRD1 gene expression in the severe spermatogenic defects examined in this study, leads us to speculate that the molecular alterations affecting piRNAs and their machinery are involved in human infertility." (PMID 23112866, 2012).
male infertility (3 papers, 2012 to 2022). The inability of the male to effect fertilization of an ovum after a specified period of unprotected intercourse. "Previous studies have shown that hypermethylation of the PIWIL2 and TDRD1 promoter regions, which are involved in the PIWI-piRNA pathway, is associated with abnormal DNA methylation and male infertility in humans." (PMID 35315771, 2022). "Remarkably, the transcripts encoding genes such as ZMYND15, KLHL10, TDRD1, TSSK2 and DNAJB13, which are linked to male infertility in other species, were differentially expressed among the treatments." (PMID 30697164, 2018). "DNMT3L as well as PIWIL2 and TDRD1 null models revealed a loss of methylation at LINE-1 and intracisternal A-particle (IAP) transposons, leading to reactivation of repetitive elements that contribute to meiotic arrest and male infertility." (PMID 23112866, 2012).
Azoospermia (2 papers, 2019 to 2020). Absence of any measurable level of sperm,whereby spermatozoa cannot be observed even after centrifugation of the semen pellet. "Interestingly, we identified meiotic proteins a priori unrelated to the UPS such as DAZL (deleted in azoospermia), SPAG1 (Sperm-associated antigen 1), SPATA5/20 (Spermatogenesis-associated protein 5/20), the tudor domain proteins TDRD1/6/9, MAEL (repressor of transposable elements), and RNF17." (PMID 31437213, 2019).
hepatocellular carcinoma (1 paper, 2013). A malignant tumor that arises from hepatocytes. "TDRD1, which is known to be specifically expressed in the testis is expressed in both hepatocellular carcinoma and non-tumorous liver tissues." (PMID 23135352, 2013).
melanoma (1 paper, 2024). A malignant, usually aggressive tumor composed of atypical, neoplastic melanocytes. "Interestingly, several exclusively mutated genes in murine dormant cells such as ZFPM2, PRKDC, TDRD1, NES, CDC42BPBD and HX57, exhibited moderate to high frequencies of mutation in human melanoma." (PMID 39223638, 2024).
nasopharyngeal carcinoma (1 paper, 2021). A carcinoma arising from the nasopharyngeal epithelium. "Additionally, TINCR can interact with ATP-Citrate Lyase (ACLY), BRAF, and Staphylococcal Nuclease and Tudor Domain Containing 1 (SND1) in nasopharyngeal cancer, non-small cell lung cancer, and post-burn skin fibroblasts, respectively." (PMID 34057016, 2021).
renal cell carcinoma (1 paper, 2020). "Downregulation of piRNA pathway genes in cancer may be uncommon but have been reported in testicular germ cell tumor (PIWIL1, PIWIL2, PIWIL4 and DDX4) and renal cell carcinoma (PIWIL1, PIWIL2 and PIWIL4) and now, also in our expression study for PIWIL2, PIWIL4 and TDRD1." (PMID 33374923, 2020).
tumor (7 papers, 2019 to 2024). "For the HER2-related C/T markers DMRTC2 and TDRD1, only one tumor in the analyzed dataset was positive for TDRD1." (PMID 38467851, 2024). "TDRD1 is responsible for coding a protein containing a tumor domain that suppresses transposable elements during spermatogenesis." (PMID 36497036, 2022). "The expression in this tumor is due to the activation of TDRD1 primarily in tumor cells, with no obvious subclonality." (PMID 38467851, 2024). "Mechanistically, we showed that AEG-1 palmitoylation adversely regulates its protein stability and weakens AEG-1 and staphylococcal nuclease and tudor domain containing 1 (SND1) interaction, which might contribute to the alterations of the RISC activity and the expression of tumor suppressors." (PMID 36276642, 2022).
cancer (6 papers, 2013 to 2025). A tumor composed of atypical neoplastic, often pleomorphic cells that invade other tissues. "These cells were able to recognize specific peptides that make up the FGFR2-tudor domain containing 1 (TDRD1) protein breakpoint in cancer cells." (PMID 38213535, 2023). "Our comprehensive analysis revealed a more differentiated pattern where PIWIL1, MAEL and HENMT1 had increased expression, while PIWIL2, PIWIL4 and TDRD1 had decreased expression when comparing benign and malignant tumor samples." (PMID 33374923, 2020). "Although we detected high levels of ERG mRNA in several cancer cell lines derived from the hematopoietic lineage, the corresponding expression of TDRD1 mRNA was approximately 50-fold lower than in VCaP cells." (PMID 23555854, 2013). "TDRD1 has been initially identified as a cancer/testis antigen, i.e. a gene which is expressed in the testis and cancer, but silent in adult somatic tissues." (PMID 23555854, 2013). "Some of these pathway genes (PIWIL1, PIWIL2, TDRD1 and MAEL) are categorized as cancer/testis genes due to their restricted expression in testis but in recent years, have been observed to be aberrantly expressed in multiple cancers." (PMID 33374923, 2020). "As for TDRD1 and PLA2G7, progression-associated overexpression of CACNA1D may be largely independent of ERG-status in these cancers, and apparently occurs also in ERG-negative cancers." (PMID 27196083, 2016). "In contrast, as a cancer/testis antigen, TDRD1 is not expressed in healthy somatic tissues." (PMID 23555854, 2013).
benign tumors (1 paper, 2020). "TDRD1 expression was reduced in HGSOC compared to benign tumors and expression was significantly lower in late stage tumors compared to benign tumors." (PMID 33374923, 2020). "Methylarginine binding genes TDRD1 and TDRD9, had overall low expression in HGSOC and benign tumors." (PMID 33374923, 2020).
Hematopoietic Cancers (1 paper, 2013). "We thus investigated ERG and TDRD1 co-expression by qRT-PCR in a panel of cell lines representing various hematopoietic cancers." (PMID 23555854, 2013).
TDRD1 also shares sentences with these, for which no sentence is quoted: acute myeloid leukemia (1 paper); Atrophy (1); breast tumors (1); liver cancer (1); liver diseases (1); non-small cell lung carcinoma (1); prostatic intraepithelial neoplasia (1); seminoma (1); Sertoli Cell-Only Syndrome (1); testicular germ cell tumor (1); testicular tumors (1).